C3orf52 (chromosome 3 open reading frame 52)
Description:
Has a role in LIPH-mediated synthesis of 2-acyl lysophosphatidic acid (LPA). LPA is a bioactive lipid mediator involved in different biological processes, and necessary to promote hair formation and growth.
Synonyms: TTMP; FLJ23186; HYPT15
Tractability: Antibody: UniProt places it where antibodies can reach, with high confidence; its Gene Ontology location is reachable by antibodies, with high confidence; UniProt predicts a signal peptide or a membrane-spanning region.
Gene: Protein-coding gene on chromosome 3 (112,086,335 to 112,131,004, forward strand). Ensembl gene ENSG00000114529.
Subcellular location: Endoplasmic reticulum; Cell membrane
Gene Ontology:
Molecular function: protein binding
Cellular component: plasma membrane; endoplasmic reticulum
Genetic constraint (gnomAD): Loss-of-function variants: 17 observed, 19.09 expected, observed/expected ratio (o/e) 0.89, 90% interval 0.61 to 1.34. The upper end of that interval is the gene's LOEUF score, 1.34, which puts it in group 5 of 6, group 1 being the genes least tolerant of losing a copy. Missense variants: 216 observed, 220.63 expected, observed/expected ratio (o/e) 0.98, 90% interval 0.88 to 1.1. Synonymous variants: 78 observed, 84.66 expected, observed/expected ratio (o/e) 0.92, 90% interval 0.77 to 1.11.
Homologues: Orthologues: chimpanzee C3H3orf52 (97% identical), macaque C2H3orf52 (88% identical), guinea pig C3orf52 (74% identical), rabbit C3orf52 (74% identical), pig C3orf52 (74% identical), mouse BC016579 (68% identical), dog C3orf52 (64% identical), rat C11h3orf52 (64% identical).
Diseases named in the same sentence as C3orf52 in open-access papers:
C3orf52 is named in the same sentence as 4 diseases in open-access papers, as found by Europe PMC text mining. Sharing a sentence is not in itself a finding about the gene and the disease. The quoted sentences say what the papers report.
metastatic tumor (1 paper, 2016). "Expression levels of miR-200a, miR-200b, miR-429, miR-30a-5p, miR-30a-3p, miR-30e, miR-30e-3p, CDH1, SLC22A24, C3orf52 and FREM1 were significantly decreased in metastatic (TNM stage III with pN+ and IV) compared to non-metastatic tumor (TNM stage I and II)." (PMID 27549611, 2016).
tumor (1 paper, 2016). "In our study, CDH1 was one of seven EMT-associated genes (CDH1, SCD, PAPSS2, C3orf52, FREM, SLC22A24, SLC25A29) successfully validated to be deregulated in tumor tissue." (PMID 27549611, 2016).
C3orf52 also shares sentences with these, for which no sentence is quoted: hypotrichosis (1 paper); pancreatic adenocarcinoma (1).